RPS2 (ribosomal protein S2)
Diseases named in the same sentence as RPS2 in open-access papers (continued):
Sharing a sentence is not in itself a finding about the gene and the disease.
infection (27 papers, 2012 to 2025). The state of being infected such as from the introduction of a foreign agent such as serum, vaccine, antigenic substance or organism. "In this study, 149 DEGs that encoded disease resistance genes, e.g. RPM1 and RPS2, were differentially regulated at the site of infection." (PMID 28860643, 2017). "Immediately following pathogen infection, avrRpt2 and RPS2 induce AIG1 (avrRpt2 induced gene 1), which may cause cell death." (PMID 37821523, 2023). "Notably, HSPs likely associated with R proteins such as RPM1 and RPS2 in the development of ETI during infection." (PMID 32293256, 2020). "At 2 DAI, genes involved in effector-triggered immunity (ETI) were observed, such as NLRs RIN4 and RPS2, which play a central role in plant resistance following pathogen infection." (PMID 40970172, 2025). "In addition, this study also found that RPS2 gene family members in the plant-pathogen interaction pathway in Coptis were significantly upregulated after root rot pathogen infection, suggesting that pathogen infection caused resistance responses in the rhizome of Coptis." (PMID 36809123, 2023). "In this study, two lncRNAs (lncRNA53468 and lncRNA40596) and their target genes RPM1 and RPS2 were significantly upregulated after infection in the plant–pathogen interaction pathway, compared with uninfected plants." (PMID 37229126, 2023). "For example, RPS2 works as a membrane receptor binding to viral envelope protein E in the infection of DENV and YFV." (PMID 35129423, 2022). "In contrast, almost 100 transcripts related to genes typically involved in viral protein translation during infection (e.g. rps2, 12, 14; wdr12; rpf2; nip7; eif4; eif4ebp3l; eif4a3; eif4ea; eif4b) were down-regulated." (PMID 35710351, 2022). "In contrast, after an infection that leads to strong pathogen recognition via the cytoplasmic immune receptor RPS2, ALD1 acts additively with both NPR1 and ICS1/SID2 to suppress pathogen growth." (PMID 36523630, 2022). "At 2 d.p.i of AvrRpt2 infection, the leaves of rps2 and atg4a4b were only yellowed, while the leaves of npr1 and atg8a were especially degraded." (PMID 32708160, 2020). "ATG knockout mutants display impaired autophagy activity and fail to regulate hypersensitive response (HR)-PCD that initiated by Psm ES4326/AvrRpt2 (AvrRpt2) infection, which are recognized by Arabidopsis R proteins resistant to Pseudomonas syringae 2 (RPS2)." (PMID 32708160, 2020). "The se-1 mutant also showed delayed HR after infection with Pst (avrRpt2), indicating a weaker or slower RPS2-mediated defence response against Pst (avrRpt2)." (PMID 27108563, 2016). "RIN4, guarded by RPM1 and RPS2, is phosphorylated upon infection with P. syringae by AvrRpm1 and AvrB." (PMID 24918296, 2014). "AIG2 was one of the first genes isolated that exhibited RPS2- and avrRpt2-dependent transcript induction early after infection with P. syringae strains carrying avrRpt2." (PMID 23372747, 2013). "Immediately after pathogen infection, AIGl is induced by avrRpt2 and RPS2, and may play role in inducing cell death." (PMID 34785701, 2021). "Moreover, the RPM1 and RPS2 proteins work together to maintain RIN4 expression levels during pathogen infection." (PMID 32293256, 2020). "RPS2 and RPM1 confer resistance against infection by avirulent Pseudomonas syringae carrying AvrRpt2 and AvrRpm1, respectively." (PMID 36523630, 2022). "The expression levels of RIN4, RPM1, RPS2, NPR1, and TGA were significantly up-regulated at all infection stages." (PMID 34630478, 2021). "Intracellular immune receptors, such as RPS2, initiate the effector-triggered immune response (ETI) by recognizing effectors such as Pseudomonas syringae's AvrRpt2 at the site of pathogen infection." (PMID 33894200, 2021).
infection (continued). "ROC1 plays an essential role in plant–pathogen recognition by promoting the P. syringae AvrRpt2 protease maturation; this effector protein is secreted in plant cells during infection and activates ETI following its recognition by the RPS2 immune receptor." (PMID 33894200, 2021). "Some genes have been found to be upregulated only at the late phase of infection such as macroglobulin/complement, serine protease inhibitor, C-type lysozyme (LYSC11) and the 40S ribosomal protein S2 (RpS2)." (PMID 32758286, 2020). "Therefore, RPM1 and RPS2 may be key proteins during infection." (PMID 32293256, 2020). "We used mCherry-tagged bacteria and observed that inoculation with either Pst DC3000 EV (virulent) or Pst DC3000 AvrRpt2 or Pst DC3000 AvrRps4 (activating the CNL RPS2 or the TNL RPS4, respectively) induced a pattern of PR1 expression at the border of the infection site." (PMID 36893276, 2023). "The auxin level of Arabidopsis, lacking a functional RPS2 gene (rps2 mutant), is increased after infection with Pseudomonas syringae pv." (PMID 35886990, 2022). "Although RPS2- and RPM1-mediated immunity require common genes (e.g., NON-RACE-SPECIFIC DISEASE RESISTANCE1 [NDR1]), RPS2 signaling results in stronger SA-related defenses upon infection." (PMID 36523630, 2022). "At 1 d.p.i of AvrRpt2 infection, rps2 and atg4a4b had no obvious plaques, while the leaves of npr1 and atg8a (ATG8a deletion mutant) shrunk." (PMID 32708160, 2020). "It has been reported that the RPS2, a CC-NB-LRR-type R-gene, induced NPR3 and NPR4 and activated JA synthesis via the degradation of JAZ1 proteins in response to hemibiotrophic pathogen infection." (PMID 32121557, 2020). "The rin4 mutants cannot survive in the presence of wild-type RPM1 and RPS2, due to strong activation of defense responses independent of pathogen infection." (PMID 24918296, 2014). "We found that while DEX-induced expression of AvrRpt2 alone was sufficient to trigger phosphorylation of eIF2α in an RPS2-dependent manner, Psm and Psm/AvrRpt2 had the same effect on eIF2α, indicating that eIF2α phosphorylation occurs not only during ETI but also during a successful infection." (PMID 36801014, 2023). "We confirmed the specific requirement of the ADR1 family in both RPS2- and RPP4-mediated resistance, as there was no significant increase in susceptibility in the helperless mutant compared to the adr1 triple in our Pst DC3000 AvrRpt2 and Hpa Emwa1 infection assays." (PMID 32925907, 2020).
tumor (22 papers, 2006 to 2025). "The human ribosomal protein S2 (RPS2), which has been implicated in multiple types of tumours, contains an N-terminal arginine and glycine-rich repeat region targeted by PAD4 for citrullination and PRMT3 for methylation." (PMID 37778382, 2023). "Ribosomal proteins (e.g., ribosomal protein L4, 5, 7a, 8, 9, 10, 10a, 11, 12, 13, 14, 18, 18a, 19, 23, 26, 27, 27a, 28, 32, 36, 37a, ribosomal protein S2, 4, 5, 6, 8, 11, 12, 13, 15a, 18, 19, 24, 25, 27, 31 and ribosomal protein P0 variant) are molecules important for tumor growth and survival." (PMID 19017389, 2008). "Of all the expression comparison between tumor and normal, only RPS2 was upregulated in tumor compared to normal in READ." (PMID 35127345, 2022). "Tumor modeling studies in mice have demonstrated that tumors overexpressing uS5 (rpS2) can be eradicated by therapeutically targeting this gene." (PMID 28085118, 2017). "Western blots indicated benign prostate did not express the protein, whereas malignant prostate cancer expressed PCADM-1 and the amount of RPS2 expressed increased with the tumor grade." (PMID 19138403, 2009). "We believe that targeting one or more of these ribosomal proteins (i.e. RPS2 or S3a) may lead to development of a highly effective treatment for prevention of cancer, eradication or primary tumors or a blockade of tumor metastasis." (PMID 19138403, 2009). "We interpret this to mean that the over-expression of RPS2 might promote ribosomal biogenesis and growth of tumor cells and that the tumor cells acquire a dependence on RPS2 for survival." (PMID 19138403, 2009). "We have also developed a SCID mouse tumor model with PC-3ML cells to determine whether DNAZYM-1P targeting of RPS2 compromised tumor growth and mouse survival rates in vivo." (PMID 19138403, 2009). "Thus, aberrant over expression of RPS2 or the mutant form of RPS2 (termed PCADM-1) might somehow activate oncogenes involved in tumor development." (PMID 19138403, 2009). "Lastly, we validated the expression of the five RBRS genes (RPL38, RPS2, RPS14, RPS19, and RPS28) using qRT-PCR on tumor and adjacent normal samples from 12 ccRCC patients at Meizhou Hospital." (PMID 40642093, 2025). "Further, we detected several genes that were both mutated and differentially spliced in the same cell types, such as HMGN3 and UBE2G2 in tumor cells, CD74 and IFI30 in myeloid cells, and RPS2 in endothelial cells indicating their important roles in tumorigenicity." (PMID 37433798, 2023). "coli), RPLP0 (tumor progression, invasion, metastasis), RPS5, RPL9, RPS14, RPS2, RPL3, and RPL23." (PMID 34445327, 2021).
cancer (11 papers, 2009 to 2026). A tumor composed of atypical neoplastic, often pleomorphic cells that invade other tissues. "Knockdown of RPS2 or TMEM177 in CRC cells resulted in anti-cancer effects and disruption of MMP and OXPHOS." (PMID 41597199, 2026). "In the cluster of RPs that have positive dysregulation scores across distinct cancers we identified several proteins, some of which had been previously associated with increased proliferation phenotypes, such as RPL36A and RPS2." (PMID 27884178, 2016). "In this context, the effect of TX to inhibit RpS2 expression and thereby stabilize it in cells indicates that TX may have anti-cancer function." (PMID 29190643, 2017). "In the gene cluster exhibiting a consistent positive dysregulation score in distinct cancer types (red line) we identified proteins that have been previously associated with increased proliferation phenotypes, such as RPL36A and RPS2." (PMID 27884178, 2016). "Thus, rps2 might promote cancer and be an excellent therapeutic target for the treatment of the diseases." (PMID 29190643, 2017). "Thus, RPS2 or other aberrantly over-expressed ribosomal proteins might promote cancer and be excellent therapeutic targets for treatment of the disease." (PMID 19138403, 2009). "These included RPL6, RPL7, RPL18A, RPS2, EIF3E, EIF3J, and UBA52, reflecting the elevated protein synthesis demands of cancer cells." (PMID 41228302, 2025).
RPS2 also shares sentences with these, for which no sentence is quoted: lymphoma (2 papers); viral infection (2); acute myeloid leukaemia (1); astrocytoma (1); breast tumor (1); cardiovascular disease (1); Cognitive impairment (1); diabetes (1); Diamond-Blackfan anemia (1); endothelial dysfunction (1); ependymoma (1); glioblastoma (1); head and neck cancer (1); latent infection (1); liver cancer (1); lung carcinoma (1); macrosomia (1); neurodegenerative disease (1); pancreatic cancer (1); Premature ovarian insufficiency (1); tauopathies (1); uterine diseases (1).